IL9 (interleukin 9)
Diseases named in the same sentence as IL9 in open-access papers (continued):
Sharing a sentence is not in itself a finding about the gene and the disease.
asthma (continued). "group had lower airway hyperresponsiveness, percentages of γδTCR+CD3+ and IL-9+CD3+ lymphocytes, and IL9+γδT cells, and higher percentages of IL-10+CD3+ lymphocytes and IL-10+γδT cells compared to the asthma control group." (PMID 27518187, 2016). "We demonstrate here that Itk also plays an important role in the expression of IL-9 and the induction of Th9 cells, a CD4+ T-cell subset relevant to asthma pathology." (PMID 26936133, 2016). "IL-9 is a pleiotropic Th2 cytokine released by a subset of CD4+ cells designated Th9 cells and has been identified as a candidate cytokine for asthma pathogenesis." (PMID 23671562, 2013). "Two first-in-human, open-label dose-escalation trials of a monoclonal antibody against IL-9, MEDI-528, in normal subjects and subjects with mild asthma have been successfully completed, showing some evidence of efficacy." (PMID 24032029, 2013). "There is evidence that treatment of allergic asthmatics with inhaled steroids was able to reverse the high levels of IL-5, IL-13 and IL-9 produced by ILC2s via STAT3, STAT5, STAT6, JAK3 and MEK signaling pathways, which was accompanied by better asthma control." (PMID 39452061, 2024). "The results of the MR analysis showed that asthma increased the levels of IL-5 and IL-9, but did not affect levels of other cytokines." (PMID 39175819, 2024). "Lower serum levels of IL-9 appeared to be related with uncontrolled asthma, but statistical significance was not reached." (PMID 39685659, 2024). "Serum levels of IL-9 appeared to be related to uncontrolled asthma, although statistical significance was not reached (OR = 0.83, 95% CI 0.63–1.09; p = 0.178)." (PMID 39685659, 2024). "In peripheral blood of patients with allergy and asthma, allergen-specific CD4+ T cells secreted IL-9, which was significantly reduced after successful immunotherapy, suggesting that IL-9 was an important secreted product of long-term stimulation of allergenic T cells." (PMID 36524132, 2022). "Moreover, a significant changes of several cytokines related to Th9 cell differentiation in mouse asthma model was detected compared with the control mice group, including forkhead box O1(FOXO1), IL-4, IL-9, IRF4, Spi1, BATF, and IRF1." (PMID 36253857, 2022). "Wild-type DC10 ablated the OVA-asthma phenotype via induction of Foxp3+ Treg responses, but CD40-/- DC10 had no discernible effects on primary facets of the phenotype (e.g., IL-5, IL-9, IL-13 levels, IgE & IgG1 antibodies; p>0.05) and were ≤40% effective in reversal of others." (PMID 33793599, 2021). "ILC2s do not depend on T cells and secrete a large number of type 2 cytokines (such as IL-4, IL5, IL-9, and IL-13) under the function of IL-25, IL-33 and thymic stromal lymphopoietin (TSLP) to participate in asthma, virus infection and worm-host defense related with the type 2 immune response." (PMID 33514798, 2021). "T cells from children with a diagnosis of asthma have increased production of IL-9, compared to children that are atopic but do not have physician-diagnosed asthma." (PMID 32985505, 2020). "Asthma pathogenesis primarily involves activation of eosinophils and CD4+ T cells, with downstream inflammation mediated mainly by Th2-type cytokines (IL-3, IL-4, IL-5, IL-9, IL-13, and granulocyte macrophage colony-stimulating factor)." (PMID 30126769, 2019). "The primary inflammatory lesion of asthma is accompanied by the accumulation of cluster of differentiation 4+ (CD4+) Th2 cells and Eos’s in the airway mucosa and its secretion of a series of cytokines, mostly IL-4, IL-13, IL-5, and IL-9." (PMID 28678189, 2017). "IL-9-targeted therapy may offer a new approach to treating patients with asthma, but clinical studies are not well underway." (PMID 37377958, 2023). "In human asthma-associated CD4 T cells, SPI1 (the gene encoding PU.1) is notably not upregulated in Th2 cells, even when analysis is focused on those cells producing IL-9." (PMID 37163370, 2023).
asthma (continued). "Moreover, our study indicated that p38α signaling in DCs was not required for IL-9 production during asthma development." (PMID 35551270, 2022). "Early studies in patients with mild asthma have shown that CD4+ T cells favour Th2 type immune responses in BALF, lung tissue, and blood, and secrete large amounts of cytokines, such as IL‐4, IL‐5, IL‐13 and IL‐9, while Th1‐type cytokines such as IFN‐γ, IL‐2 and IL‐12 are reduced." (PMID 33124760, 2020). "While asthma involved pathways like NFAT in regulation of the immune response and other lymphocyte activation pathways including signaling through IL-4, IL-8, IL-3 and IL-9 in CD8+ cells, the most prominent pathway in CD4+ cells was VDR/RXR activation signaling." (PMID 32900903, 2020). "However, the humanized anti-IL-9 antibody MEDI-528 did not decrease asthma exacerbation rates and did not improve Asthma Control Questionnaire 6 scores or FEV1 values." (PMID 31284537, 2019). "However, a study indicated that the forced expiratory volume in 1 s (FEV1) level, incidence of asthma exacerbation, and quality of life in patients failed to benefit from treatment with the humanized IL-9 neutralizing antibody MEDI-528, also known as enoclizumab." (PMID 39060923, 2024). "Therefore, a randomized, placebo-control, double-blind, multicenter, parallel-group study on an anti-IL-9 monoclonal Ab in patients with uncontrolled moderate-to-severe asthma was performed in 2013; however, no significant improvements in predicted FEV1 % were obtained." (PMID 31216735, 2019). "Serum levels of IL-9 were higher in controlled asthma, but the NCR+ILC3 cell population was higher in uncontrolled asthma, although differences were not significant." (PMID 39685659, 2024). "Of note, the equal IL-9 and IL-5 production in the CLA− T-cell coculture is of particular interest since anti-IL-5 therapy has proven to be successful in extracutaneous allergic diseases such as asthma, but not in AD, considered a CLA+-driven disease." (PMID 39201262, 2024).
Allergy (89 papers, 2005 to 2026). An allergy is an immune response or reaction to substances that are usually not harmful. "Th9 cells are a CD4 T cell subset that produces interleukin-9 (IL-9), a pleiotropic cytokine implicated in allergies, autoimmunity and cancer." (PMID 41030439, 2025). "Elevated levels of IL-4 and IL-9 suggest a Th2 profile of the inflammatory response associated with allergy and IL-13 response." (PMID 41239983, 2025). "The hallmark cytokine produced by Th9 cells is IL-9, which is closely associated with allergies and autoimmunity." (PMID 40552264, 2025). "The production of IL-9 is associated with the Th2 phenotype in allergies, and IL-9 is involved in allergic reactions in asthmatic patients through an increased expression of T cells obtained from bronchoalveolar lavage fluid." (PMID 36430483, 2022). "IL-9-producing CD4 T (Th9) cells have been implicated in allergy and tumor immunity, but how their differentiation is regulated by TGFβ is still unclear." (PMID 36241625, 2022). "IL-5, IL-9, IL-10, IL-23, and IL-27 are also related to the Th2 response (T-cell response associated with allergies, progressive systemic sclerosis, and autoimmune disorders)." (PMID 36439158, 2022). "Expression of allergy-associated cytokine genes, including Il4, Il5, Il9, Il13, and Il21, was higher in Nr4a-TKO cells, even when compared with Foxp3-KO cells." (PMID 33665581, 2021). "IL-9 is a pleiotropic cytokine implicated in mast cell development and an important mediator of allergic diseases." (PMID 35387064, 2021). "Similar to allergies, helminth infections induce a Th2 immune response associated with cytokines such as interleukin (IL)-4, IL-5, IL-9, IL-13, and increased levels of eosinophils, basophils, mast cells and circulating IgE Abs." (PMID 32268573, 2020). "Over the past years, a new subset of CD4 + T named as T helper 9 cells that secrete interleukin-9 (IL-9) as a signature cytokine is associated with tumor immunity and allergy." (PMID 33213045, 2020). "In fact, even though IL-9 has been considered to be a Th2 cytokine that participates in allergic diseases, the latest results pointed out that IL-9 is implicated in tumor immunity regulated by mast cells and Tregs." (PMID 32102441, 2020). "Since IL-9 is primarily associated in allergic inflammation, the functions of Th9 cells was found to be associated in allergic diseases." (PMID 31164892, 2019). "IL-9, and the cells that produce it, are linked to tumor immunity, immunity to pathogens, allergy, and autoimmune disease." (PMID 30442929, 2018). "Although IL-9 is more frequently associated with allergy, its role in Th1-mediated inflammation has been recently reported." (PMID 28289333, 2017). "Interleukin 9 causes airway inflammation in both infectious and allergic diseases." (PMID 40519915, 2025). "Interestingly, the anti-inflammatory IL-10 and the allergy-associated cytokines, IL-9 and IL-13, were also significantly lower in FHL1−/− than WT mice at both time points." (PMID 37884534, 2023). "IL-9 has traditionally be associated with Th2 response in allergy and helminth infections." (PMID 35921962, 2022). "By contrast, clinical allergy is caused by dysregulated type 2 immunity, which is characterized by expansion of T helper 2 (Th2) cells and eosinophils, as well as overproduction of the associated cytokines IL-4, IL-5, IL-9, and IL-13." (PMID 35281022, 2022). "In addition to IL-9, IL-33 is also a crucial regulator of MC functions and both IL-33 and MC have been influentially associated to the pathophysiology of allergic diseases and inflammation." (PMID 28090087, 2017). "Allergy is a type I hypersensitivity reaction involving Th2 cells that produce Interleukin (IL)-4, IL-5, IL-9, and IL-13." (PMID 41596388, 2026). "Despite the proven role of IL-9 in inflammation, resolution and tolerance during autoimmunity, allergy and parasitic infections, its role as a possible mediator of inflammation during metabolic diseases has been largely underexplored." (PMID 40962954, 2025).
Allergy (continued). "There is also an IL-9 single-producing T cell subset, namely the Th9 cell, which plays a dominant role in the onset of allergic diseases compared with traditional Th2 cells." (PMID 41451507, 2025). "Originally, IL-9 has been described to be involved in autoimmune diseases, allergic reactions, and parasitic infections." (PMID 40497965, 2025). "Collectively, the cellular effects of IL-9 support its diverse roles in mucosal host defense, allergic disease, autoimmunity and anti-tumor immunity, as described next." (PMID 41030439, 2025). "While IL-9 is recognized to exert multiple functions in various types of cells, it has been noted that IL-9 plays a role in T-cell biology, particularly in pathologic conditions including allergy and autoimmunity affecting specific tissue lesions." (PMID 39403384, 2024). "The roles of IL-9 and T helper 9 (Th9) Cells in allergic diseases have received increasing attention, and IL-9 is recognized as an important factor in type 2 inflammation." (PMID 38380314, 2024). "IL-9-producing Th9 cells play a role in enhancing immunity against parasites and cancer but are highly affected by allergic disease and colitis." (PMID 37740213, 2023). "Taken together, our findings suggest that DUSP8 is a T cell biomarker and potential therapeutic target for IL-9-mediated allergic diseases." (PMID 37909329, 2023). "ILC2s are characterized by the expression of cytokines associated with the type 2 immune response, including IL-4, IL-5, IL-13 and IL-9, all important in the regulation of immunity against helminth parasites and allergies." (PMID 35711429, 2022). "They regulate immunity against helminth parasites and allergies by expressing type 2 immune response cytokines including IL-9, known to be critical for inducing and potentiating the immune response in such context." (PMID 35711429, 2022). "In contrast, Th2 cells, which produce IL-4, IL-5, IL-6, IL-9, IL-10, and IL-13, induce strong antibody responses by B cells, induce eosinophil activation, and are responsible for allergic reactions." (PMID 35646978, 2022). "These function as alarm signals activating ILC2s to produce the Th2 cytokines IL-4, IL-13 and IL-9, with critical roles in type 2 immunity and allergy." (PMID 33803079, 2021). "ILC2s respond quickly to allergic reactions mainly by secreting type 2 cytokines and other peptides, such as IL-4, IL-5, IL-13, IL-9, and amphiregulin (Areg), and by intercellular regulation of the cell-to-cell pathway." (PMID 34177881, 2021). "Recently, an IL-4-BATF axis was identified in the regulation of IL-9 producing mucosal mast cell (MMC9) function during IgE mediated food allergic reactions." (PMID 35387064, 2021). "IL-9 was initially studied in allergic diseases, where it exerts a detrimental pro-inflammatory activity by promoting the expression of the Th2-related chemokines CCL17 and CCL22, known to be associated with allergic inflammation." (PMID 34944921, 2021). "ILC2s synthesize and secrete Th2 cytokines (IL-4, IL-5, IL-9, and IL-13), which promote eosinophils and mast cells to participate in allergic reactions." (PMID 34659628, 2021). "For example, IL-9 has impact on the development of the allergic disease by taking function in enhancing the synthesis of IgE and maturation of mast cell." (PMID 32883301, 2020). "In previous studies, IL-9 was mainly involved in the development of allergic diseases, autoimmune diseases and parasite infections." (PMID 32228589, 2020). "It is established knowledge in the allergy field that Th2-derived IL-9 and IL-4/IL-5 induce goblet cell hyperplasia either directly or indirectly via neutrophilic granulocytes, respectively." (PMID 30845208, 2019). "Meanwhile, the late phase of an allergic reaction occurring hours after sensitisation will trigger the release of cytokines such as IL-4, IL-5, IL-9, IL-13, TNF-α and IFN-γ that will recruit inflammatory cells and further bring about mast cell degranulation." (PMID 31829185, 2019).
Allergy (continued). "Th9 cells act in parasite infections, allergic diseases, autoimmunity, and tumor suppression mainly through secreting IL-9." (PMID 32082072, 2019). "Whereas, late phase of the allergic reaction is recognized by the release of cytokines such as IL-13, IL-4, IL-9, IL-5, IFN-γ and TNF-α after 2 to 6 h of sensitisation." (PMID 31829185, 2019). "Interleukin-9 (IL-9) is important for allergy, autoimmunity and tumor immunity, but how its expression is regulated is unclear." (PMID 30442929, 2018). "T helper 9 (Th9) cells contribute to lung inflammation and allergy as sources of interleukin-9 (IL-9)." (PMID 28090087, 2017). "In the present study, we determine the contribution of IL-9 to Aspergillus infection and allergy in murine and human CF, and assess the therapeutic effectiveness of targeting IL-9-dependent pathways and the diagnostic potential of this approach." (PMID 28090087, 2017). "Recent studies suggest that IL-9 mediated both antimicrobial immune and autoimmune responses in addition to allergic diseases." (PMID 27766098, 2016). "Elevated production of IL-9 plays an important role in autoimmune processes, allergy, and antitumor immunity." (PMID 26583100, 2015). "Elevated IL-9 production and Th9 differentiation have been demonstrated in mouse models of allergy and melanoma." (PMID 26583100, 2015). "In allergic diseases, IL-9 production can also occur in mast cells, in part through stimuli such as histamine, IL-1, antigen-specific immunoglobulin E and antigen, and IL-9 itself, and can help to facilitate their growth and expansion." (PMID 26078482, 2015). "It is known that IL-9 is a Th2-type cytokine, which acts in a variety of inflammatory cells and tissue cells and plays important roles in parasitic infections and allergic diseases, especially allergic reactions, asthma, and so on." (PMID 24799769, 2014). "Type 2 response is related to secretion of IL-4, IL-5, IL-9 and IL-13 which promote induction of IgE and allergic response." (PMID 20184725, 2010). "Allergic diseases are characterized by the presence of Th2 cells and related cytokines, such as interleukin-4 (IL-4), IL-5, IL-9, and IL-13 with the subsequent development of eosinophils infiltration and chronic inflammation." (PMID 16677403, 2006). "The findings raise the possibility that the beneficial effects of glucocorticoids in the treatment of allergic diseases are in part mediated by inhibition of IL-9 production." (PMID 15840176, 2005). "It remains to be determined whether patients with allergies experience a more pronounced increase in Th9 cell counts and IL-9 following ICI treatment." (PMID 40248207, 2025). "Delineating the mechanisms regulating IL-9 production may have implications for the treatment of allergies, inflammatory bowel diseases and tumors." (PMID 39763655, 2024). "A comprehensive understanding of how lipid metabolism regulates IL-9 may help us to better understand links between obesity, allergies and inflammation." (PMID 39763655, 2024). "Our findings and the database information support that DUSP8 is a key activator of IL-9 production and may be involved in human allergic diseases." (PMID 37909329, 2023). "To study whether the DUSP8–Pur-α–IL-9 axis contributes to other human allergic diseases, we further enrolled people with atopic dermatitis (AD)." (PMID 37909329, 2023). "Numerous studies have indicated the involvement of IL9 in the pathogenesis of allergic diseases." (PMID 36793899, 2023). "Interestingly, levels of IL-9 corelated with allergic reactions in the coseasonal ASIT regimen, which is also consistent with other reports." (PMID 36439113, 2022). "IL9 is mainly involved in autoimmunity, allergic reactions, and parasitic infections, and is a growth factor of T cells and mast cells; it has received increasing attention to the role of IL-9-skewed CD8+ T (Tc9) cells, mast cells, and Vδ2 T cell-derived IL-9 in tumor immunity." (PMID 36338570, 2022).